RET (ret proto-oncogene)
Diseases named in the same sentence as RET in open-access papers (continued):
Sharing a sentence is not in itself a finding about the gene and the disease.
tumor (continued). "TPX-0046 has shown potent anti-tumor activity in vitro and in vivo against various RET alterations, particularly against SFM-mediated resistance." (PMID 37568193, 2023). "Patients with RET fusion-positive PTCs were significantly younger than patients with BRAF V600E and RAS-mutated carcinomas (P < 0.001) and had significantly larger tumor than patients with the BRAF V600E-mutated carcinomas (P < 0.001)." (PMID 37882481, 2023). "Different mutation profiles of RET and BRAF genes were detected in MTC and PTC mixed-tumor foci in different cases, suggesting that the two types of cancer were driven by different genes, indicating the co-occurrence of the two independent cancers." (PMID 37580706, 2023). "In 8 cases (4.1%), a red 5′ and green 3′ RET FISH split signal was observed in ≥50% of the tumor cells, while 1 case showed a single green 3′ RET signal, which was interpreted as positive according to the guidelines." (PMID 37190044, 2023). "Regardless of prevalence, targeted therapies that specifically target altered RET have shown considerable efficacy in patients with RET fusion-positive tumours." (PMID 37277734, 2023). "RET fusion genes, as prognostic biomarkers, were correlated with tumour recurrence in early-stage resected LUAD." (PMID 37760531, 2023). "The baseline tumor characteristics and treatment responses to systemic chemo-immunotherapy from a large cohort of patients with RET fusion-positive NSCLC, untreated with SRIs, have recently been reported." (PMID 38201460, 2023). "In this cohort, we detected a RET fusion in a case with a cTF value as low as 0.27%, suggesting that the assay was able to detect fusion even with very low amount of tumor shed." (PMID 36690680, 2023). "A better outcome is observed in hereditary MTC cases detected using genetic screening of the RET proto-oncogene and treated in a preclinical phase when the tumor is microscopic and confined to the thyroid." (PMID 37568824, 2023). "Additional cell-surface IMPs were identified as upregulated exclusively only in cluster 2 (4 IMPs, including the cluster 2 “landmark” protooncogene RET) or unassigned PPGL (6 IMPs) or shared by these two tumor groups (5 IMPs)." (PMID 37749499, 2023). "The selectivity, anti-RET activity, and intracranial efficacy of APS03118 were assessed in vitro and in vivo in a variety of RET-dependent tumor models." (PMID 38201460, 2023). "GDNF-mediated activation of RET is recognized in several cancers and promotes tumor growth, invasion, and metastasis." (PMID 37691636, 2023). "Though isolated reports of acquired tumor resistance drive concerns regarding the long-term efficacy of RET-selective agents, future follow-up studies will be needed to evaluate the viability of prolonged treatment courses." (PMID 35685436, 2022). "The PHLPP1- and additional genes of the RET signalling pathway were detected in six other primary and relapse tumor samples included in the study." (PMID 36037157, 2022). "The treatment of two RET p.L629_D631delinsH MTCs, one with cabozantinib and the other with a combination of sorafenib and tipifarnib, showed a partial response, with a tumor reduction of 48% and 46%, respectively." (PMID 36091144, 2022). "RET inhibition by the small-molecule vandetanib (ZD-6474) significantly reduced tumor growth in this genetically engineered mouse model (GEMM)." (PMID 34716856, 2022). "Regorafenib, a multi-kinase inhibitor, inhibits several numbers of protein kinases implicated in tumour growth (KIT, RET, RAF-1, and BRAF p38 MAP kinase), metastasis (PDGFR- and FGFR1), and tumour angiogenesis (VEGFR-1, -2, and -3)." (PMID 36614133, 2022). "The difference between SDHB and RET-PCPG became even more evident when the tumor cells of each patient were compared to chromaffin developmental cell types." (PMID 36046044, 2022). "Aberrant RET signaling, like other oncogenes, can enhance the proliferative signaling, particularly the cell proliferation, an essential mechanism to sustain the tumor growth." (PMID 35422765, 2022).
tumor (continued). "RET/NTRK fusions were found in 43 (32.8%) tumor samples spread across various subtypes of PTC, including 22 cPTC samples, 11 dsvPTC, five fvPTC, one svPTC, one fvPTC/svPTC, one cPTC/fvPTC, and two cPTC/fvPTC/svPTC." (PMID 35015563, 2022). "Highly selective RET inhibitors have recently entered clinical use after demonstrating efficacy in treating patients with diverse tumor types harboring RET gene rearrangements or activating mutations." (PMID 35510953, 2022). "A transcriptomic analysis of 76 inherited and sporadic PPGLs identified 2 tumour clusters, one including SDHB, SDHD and VHL-mutated tumours (pseudohypoxic signalling cluster), and one comprising RET and NF1-mutated (kinase signalling cluster) tumours." (PMID 35938916, 2022). "RET fusion-positive NSCLC patients show poorer tumor cell differentiation, more signet ring cell subtypes, and smaller primary lesions (<3 cm) when compared to ALK rearrangement, EGFR receptor mutation, and ROS-1 fusion-positive patients." (PMID 36582799, 2022). "Pre-clinical and early clinical evidence suggests that RET fusions lead to oncogene addiction across tumor types and have the potential to be targeted by selective RET inhibition." (PMID 35962206, 2022). "Two recent studies of lenvatinib, a kinase inhibitor acting on the VEGFR, PDGFR, FGFR, KIT, and RET pathways, have shown exciting results in reducing tumor burden in patients with recurrent/metastatic ACC." (PMID 35205740, 2022). "In both patients, the RET fusion decreased in frequency upon selpercatinib treatment, indicating therapeutic target engagement in that tumor cell population, with one patient indeed showing a mixed response on their first scan." (PMID 35304457, 2022). "LMNB1 knockdown in lung epithelial cells promoted EMT, cell migration, tumor growth, and metastasis by activating RET/p38 signaling." (PMID 36011023, 2022). "According to another report, the expression of RET and GRFα1 is higher in tumor tissues of patients with neuroinvasive pancreatic carcinoma than in normal tissues." (PMID 35582425, 2022). "One sample with RET C630R (primary tumor from patient 1) displayed high concurrent expression of both scores." (PMID 35454858, 2022). "The current mandatory biomarkers to look for in late-stage NS-NSCLC include different genomic alterations present on EGFR, ALK, ROS1, NTRK, BRAF, MET, and RET, as well as the PD-L1 expression of tumor cells." (PMID 35565387, 2022). "Responses were observed in patients with RCC and NSCLC, and included patients with tumor RET rearrangements, and MET, CBL and AXL alterations." (PMID 35767205, 2022). "Although their efficacy against the tumor and despite their activity against RET, the first-generation MKIs approved for the treatment of MTC (i.e., vandetanib and cabozantinib) were limited in their use by the onset of the off-target toxicities." (PMID 35422765, 2022). "When targeting anti-angiogenesis, MTDs can simultaneously target multiple proteins that promote tumor growth such as RET, FLT3, and BRAF, which contribute to the overall anti-tumor effect." (PMID 35463356, 2022). "On the other hand, if specific driver mutations are identified (eg, NTRK, ALK, RET, BRAF), new mutation-specific kinase inhibitor should be considered which have been FDA-approved, specifically for TCs or for any tumor type harboring the same molecular target." (PMID 36605433, 2022). "RET mutation, especially for M918T, is common in MTC as a driver for tumor progression, including metastasis and dismal survival." (PMID 36713370, 2022). "Cabozantinib is an inhibitor of VEGFR2, MET, and RET that also binds to the ATP-binding site of RTKs, thereby inhibiting autophosphorylation of RTKs, which leads to tumor hypoxia and apoptosis and suppresses metastasis, angiogenesis, and tumor growth." (PMID 36209184, 2022).
tumor (continued). "Activity in terms of reduction of tumor volumes was noted to be significantly enhanced in patients with molecular alterations in the drug targets (RET, VEGFR, EGFR, and PI3K/mTOR), supporting further development of the combination." (PMID 34551970, 2022). "There was a higher M2:M1 ratio in cluster 1 (SDHx, VHL, FH, n = 27) tumours compared to cluster 2 (RET, n = 6) (P = 0.017) and a lower proportion of CD8 cytotoxic (Tc) lymphocytes in PPGLs with a known genetic diagnosis (P = 0.047)." (PMID 35975974, 2022). "In this line, RET is proposed to act as a tumor suppressor by promoting a transcriptional program leading to a terminally differentiated (non-malignant) neuronal phenotype." (PMID 34716856, 2022). "We aimed to determine the transcriptional programs that are active across tumor cells and then identify the programs that are differentially enriched between RET and SDHB tumors." (PMID 36046044, 2022). "In summary, this analysis suggests that during lactation abnormal RET levels drive a transcriptomic signature that is enriched in Stat-driven genes related to the tumor-promoting inflammatory-phase response at the onset of involution." (PMID 35044452, 2022). "Given the similar treatment outcomes across tumor types and alteration classes, RET-mutant and fusion-positive patients were combined for all subsequent molecular analyses." (PMID 35304457, 2022). "We show that forced RET overexpression in lactation leads to an increase in epithelial cell proliferation, which likely contributes to the higher tumor incidence of the multiparous females." (PMID 35044452, 2022). "In other patients, rare RET-wildtype tumor cell populations driven by an alternative mitogenic driver are selected for by treatment." (PMID 35304457, 2022). "In summary, NMF analysis revealed two main transcriptional programs in PCPG that separate RET from SDHB tumor cells." (PMID 36046044, 2022). "In one NSCLC patient, harboring KIF5B-RET rearrangement, circulating tumor DNA and post-mortem biopsy analysis showed the appearance of a wide spectrum of RET mutations on G810 residue (solvent front mutations), concomitantly with progression of the disease." (PMID 35422765, 2022). "A molecular analysis of tumor tissue from metastatic lesions revealed a rearrangement involving the RET gene, and the patient was subsequently treated with cabozantinib (XL184), a nonselective RET inhibitor." (PMID 35510953, 2022). "Logistic regression analysis revealed that RET-PCPG tumor cells are transcriptionally more similar to developed adrenal chromaffins, whereas SDHB-PCPG tumor cells appear to be in an earlier phase of adrenal development." (PMID 36046044, 2022). "The transcription programs related to ion channel activity (transmembrane transport) separated the SDHB and RET tumor cells." (PMID 36046044, 2022). "This review covers the current biological understanding of RET signaling, the impact of RET hyperactivity on tumor progression in multiple tumor types, and RET inhibitors with promising preclinical and clinical efficacy." (PMID 35957881, 2022). "Hierarchical clustering of metaprogram-scored cells revealed two major clusters separating RET from SDHB tumor cells." (PMID 36046044, 2022). "stressed the benefits of employing plasma NGS platforms over SoC tissue testing for comprehensive tumor genotyping, particularly when referring to rare targets such as RET." (PMID 35785173, 2022). "The introduction of the multikinase inhibitors, together with the recent more selective RET inhibitors, has opened a new phase in our treatment of these rare but fascinating tumours." (PMID 35521769, 2022). "When evaluated in RET fusion-positive preclinical models, lenvatinib effectively inhibits RET fusion kinases and RET pathway activity in vitro, and inhibits growth of RET fusion-positive tumor cells in vivo." (PMID 35957881, 2022).
tumor (continued). "Subsequently, the authors investigated the association between RET/RAS mutational status and PFS/tumor RR in the MTC patients of the EXAM trial." (PMID 35872981, 2022). "Surprisingly, SDHB tumor cells (originating from various anatomical locations) were less heterogeneous than their RET counterparts (originating from the adrenal gland)." (PMID 36046044, 2022). "EGFR and RET tumor models in Drosophila reveal decreased tumor growth and increased survival when cytoneme formation is disrupted in neoplastic cells and surrounding tissue." (PMID 35119540, 2022). "The targeted therapies are tailored to the patient based on the specific genetic background of the tumor (e.g., mutation or altered expression of EGFR, KRAS, BRAF, PIK3CA, PTEN, HER2, or gene fusion of ALK, ROS1, RET)." (PMID 35205667, 2022). "In a preclinical study, cabozantinib exhibited significant antiangiogenic and antitumor activity in a broad range of tumor models, including a model of MTC with an activating RET mutation." (PMID 35872981, 2022). "We confirmed the presence of a RET gene rearrangement from the patient’s primary tumor (1988) using fluorescence in situ hybridization (FISH)." (PMID 35510953, 2022). "RET rearrangements have been identified in tumour specimens via classic techniques, such as FISH and RT-PCR." (PMID 34503226, 2021). "The ORR was 0% for patients with tumor harboring KIF5B as fusion partner with RET, compared to 67% with non-KIF5B partners." (PMID 33671873, 2021). "Further, we detected activating mutations in KRAS, ERBB2, RET, and CTNNB1, presumably conferring a new oncogenic driver in the respective tumor." (PMID 34201252, 2021). "All our tumor samples will also be examined for somatic mutations since these are also detected in 30% of sporadic HNPGLs, mainly involving VHL, NF1, RET and HIF2α genes, although these are rarely associated with multiple HNPGLs." (PMID 34072806, 2021). "Tumor bearing RET transgenic mice were treated with the CXCR2 inhibitor SB265610, which led to a significant survival benefit as compared to mice treated with the DMSO solution (control group)." (PMID 33578808, 2021). "The human data we present here suggest that ARF expression levels are downregulated in AIP-FIPA tumours, indicating the reduced activity of the RET apoptosis pathway." (PMID 34588620, 2021). "Significant reduction in RET protein expression was noted in the tumor samples in comparison to the normal control samples." (PMID 33906292, 2021). "Tumours induced by NIH3T3 cells transfected by RET G810R and TRKA G595R featured resistance to Pz-1, demonstrating that RET or TRKA inhibition is critical for its anti-tumourigenic effect." (PMID 34373541, 2021). "Mutations involving effectors of the mitogen-activated protein kinase (MAPK) pathway such as RET, BRAF, RAS, and NTRK1 occur in approximately 70% of patients with PTC and are associated with histopathological and biological tumor behavior." (PMID 34325712, 2021). "Cell-based Pz-1 effects were translated into potent in vivo anti-tumour activity against RET or TRKA driven xenograft models." (PMID 34373541, 2021). "A recent multi-institutional study analyzed tumor and plasma biopsies from 18 patients with RET-rearranged NSCLC after treatment with selpercatinib and pralsetinib to characterize mechanisms of acquired resistance." (PMID 33806299, 2021). "Given that most nutritional interventions are prescribed in intermittent courses to limit the constraints on the users, we compared continuous versus discontinuous (1 week on, 1 week off) regimens of the KD or 3HBpo in the RET tumor model." (PMID 33320838, 2021). "We found that PMN-MDSC represent the majority of cells within the total population of MDSC in metastatic LN, BM, spleen, and peripheral blood of tumor bearing RET transgenic mice." (PMID 33578808, 2021).
tumor (continued). "Others such as ROS1 rearrangement, RET fusion, HER2 mutation, NTRK1 fusion, and BRAF V600E mutation were detected in 7.9% of CSF and 11.1% of tumor tissues but only 4% in plasma." (PMID 34671549, 2021). "MET inhibitor cabozantinib (also inhibits VEGFR2, AXL, KIT, RET) has been studied as an inhibitor of angiogenesis and tumor growth in many tumor diseases." (PMID 34212564, 2021). "In clinical settings, Chernobyl-related childhood PTC from Belarus with RET/PTC3 was associated with the shorter period of latency and more advanced tumor stage." (PMID 34282777, 2021). "Sorafenib, approved in 2008, inhibits multiple growth tyrosine kinase receptors (PDGFRs, VEGFRs, c-KIT, and RET) and their downstream tyrosine kinase cascades (Ras, Raf, Mek, and Erk) in both tumor cells and endothelial cells." (PMID 33669204, 2021). "Overexpression of RET has been reported in some tumours including breast and pancreatic adenocarcinoma." (PMID 34373541, 2021). "Lenvatinib, confirmed as an inhibitor of VEGF receptors 1–3, FGF receptors 1–4, platelet-derived growth factor (PDGF) receptor α, KIT, and RET, selectively inhibits receptor tyrosine kinases involved in tumor growth and angiogenesis." (PMID 34527576, 2021). "As reported in a large series, RET mutations are almost always mutually exclusive, and only in few cases, multiple RET somatic mutations are present, suggesting that MTC is a rather stable tumor." (PMID 33572167, 2021). "This does not negate the possible direct effect of cabozantinib on MET and RET activity in the tumor cells of the MET+/RET+ LuCaP 93 xenografts." (PMID 33471819, 2021). "RET fusions were observed in a small fraction (<1%) of metastatic CRC (mCRC), where their presence was associated with old age, right‐sided tumor origin, wild‐type RAS and BRAF, microsatellite instability (MSI)‐high tumors, and poor prognosis." (PMID 34741450, 2021). "In animals bearing LuCaP 93 tumors, cabozantinib treatment significantly decreased tumor volume (TV) in MET+/RET+ LuCaP 93 animals compared to vehicle controls (p = 0.0175)." (PMID 33471819, 2021). "Next-generation sequencing (NGS) analysis for numerous different types of patient tumors has uncovered that RET alterations can also occur in other tumor types (albeit at low frequency), including ovarian epithelial carcinoma and salivary gland adenocarcinoma." (PMID 34832869, 2021). "Our review of the literature on IMT and other kinase fusions revealed, in addition to ALK rearrangements, the potential association of ROS1, NTRK, RET, or PDGFR beta alterations with the tumor." (PMID 34011083, 2021). "We identified LuCaP 93 and LuCaP 173.1 as PDX models that would differentiate the response of a MET+/RET+ tumor from a MET-/RET- tumor to cabozantinib treatment." (PMID 33471819, 2021). "The LIBRETTO-431 trial is a phase III trial involving metastatic or stage IIIB–C naive patients not suitable for radical surgery or radiation therapy; patients must have a RET gene fusion found from a tumour biopsy or in blood samples." (PMID 34503226, 2021). "The radiogenic PTCs, especially those detected after the shorter latency, had a very high frequency of RET/PTC3 rearrangements, which is associated with more aggressive tumor phenotype and a solid-trabecular growth pattern." (PMID 34885148, 2021). "MiR-153-3p is a RET-regulated miRNA which functions as a tumor suppressor, suppressing cell proliferation, invasion or migration, while promoting apoptosis." (PMID 33924120, 2021). "In the context of complete cICB regimen (3 i.p. injections over a 6-day period), 3HBpo boosted the tumor growth–inhibitory activity of cICB, prolonging overall survival of almost 60% of RET tumor bearers." (PMID 33320838, 2021).